DNAJC19 (DnaJ heat shock protein family (Hsp40) member C19)
Description:
Mitochondrial co-chaperone which forms a complex with prohibitins to regulate cardiolipin remodeling (By similarity). May be a component of the PAM complex, a complex required for the translocation of transit peptide-containing proteins from the inner membrane into the mitochondrial matrix in an ATP-dependent manner. May act as a co-chaperone that stimulate the ATP-dependent activity (By similarity).
Synonyms: TIM14; TIMM14; Pam18
Tractability: Antibody: UniProt predicts a signal peptide or a membrane-spanning region. PROTAC: ubiquitination databases record sites on it; its protein half-life has been measured.
Gene: Protein-coding gene on chromosome 3 (180,983,635 to 180,989,774, reverse strand). Ensembl gene ENSG00000205981.
Subcellular location: Mitochondrion inner membrane
Pathways (Reactome):
Protein localization: Mitochondrial protein import
Gene Ontology:
Molecular function: protein binding; ATPase activator activity
Biological process: intracellular protein transport; protein import into mitochondrial matrix; regulation of cardiolipin metabolic process
Cellular component: mitochondrial inner membrane; mitochondrion; protein-containing complex; inner mitochondrial membrane protein complex; matrix side of mitochondrial inner membrane; membrane; PAM complex, Tim23 associated import motor; TIM23 mitochondrial import inner membrane translocase complex
Genetic constraint (gnomAD): Loss-of-function variants: 12 observed, 12.48 expected, observed/expected ratio (o/e) 0.96, 90% interval 0.62 to 1.55. The upper end of that interval is the gene's LOEUF score, 1.55, which puts it in group 6 of 6, group 1 being the genes least tolerant of losing a copy. Missense variants: 77 observed, 107.2 expected, observed/expected ratio (o/e) 0.72, 90% interval 0.6 to 0.87. Synonymous variants: 31 observed, 31.6 expected, observed/expected ratio (o/e) 0.98, 90% interval 0.74 to 1.32.
Gene-disease validity (ClinGen):
ClinGen rates the evidence that DNAJC19 causes each of these diseases.
3-methylglutaconic aciduria type 5 (autosomal recessive): Definitive. A syndrome characterized by severe early onset (before the age of three years) dilated cardiomyopathy (DCM) with conduction defects (long QT syndrome), non-progressive cerebellar ataxia, testicular dysgenesis, and 3-methylglutaconic aciduria.
Homologues: Orthologues: chimpanzee DNAJC19 (100% identical), macaque DNAJC19 (100% identical), rabbit DNAJC19 (100% identical), dog DNAJC19 (99% identical), pig DNAJC19 (97% identical), rat Dnajc19 (89% identical), guinea pig DNAJC19 (82% identical), mouse Dnajc19 (82% identical), tropical clawed frog dnajc19 (81% identical), zebrafish dnajc19 (78% identical), Drosophila melanogaster CG7394 (55% identical), Caenorhabditis elegans dnj-21 (50% identical). Paralogues in human: DNAJC15 (58% identical).
Diseases named in the same sentence as DNAJC19 in open-access papers:
DNAJC19 is named in the same sentence as 33 diseases in open-access papers, as found by Europe PMC text mining. Sharing a sentence is not in itself a finding about the gene and the disease. The quoted sentences say what the papers report.
Ataxia (16 papers, 2014 to 2024). Ataxia refers to impaired coordination of voluntary muscle movement. "Mutation of DnaJC19 (Tim14 or Pam 18), an 18 Kda J protein, cause early-childhood-onset (before 3 years) recessive dilated cardiomyopathy and cerebellar ataxia." (PMID 25071450, 2014). "Mutations in DNAJC19 preventing MAGMAS/DNAJC19 dimerization have been shown to lead to dilated cardiomyopathy with ataxia syndrome (DCMA)." (PMID 24786642, 2014). "DNAJC19 plays a crucial role in preserving mitochondrial integrity, and the mutation in DNAJC19 could induce the occurrence of dilated cardiomyopathy and ataxia syndrome." (PMID 38596213, 2024). "Interestingly, GATD3A is significantly downregulated in patient fibroblasts with a specific form of inheritable dilated cardiomyopathy with ataxia (DCMA) caused by mutations in the gene DNAJC19." (PMID 35307029, 2022). "A two-year-old male child with global developmental delay was diagnosed with 3 methylglutaconic aciduria type 5 also called dilated cardiomyopathy and ataxia (DCMA) based on homozygous likely pathogenic variants in exon 5 of the DNAJC19 gene c.250C>T (pArg84Ter)." (PMID 36004034, 2022). "Mutations in DNAJC19 are previously associated with dilated cardiomyopathy in ataxia syndrome." (PMID 34987545, 2021). "Similarly, a single point mutation in DnaJC19 (J-protein interacting partner of Magmas) resulted in the development of dilated cardiomyopathy with ataxia syndrome." (PMID 34715125, 2021). "Moreover, a homozygous intronic variant (IVS3-1G>C) in DNAJC19 (also called TIM14), affecting splicing and resulting in gene loss-of-function, has been described to cause dilated cardiomyopathy with ataxia syndrome." (PMID 35083221, 2021). "Originally identified in Alberta Dariusleut Hutterites, DnaJC19 mutations are clinically characterized by raised levels of 3-methylglutaconic acid, a readout of mitochondrial distress, dilated cardiomyopathy, prolongation of the QT interval in the electrocardiogram and cerebellar ataxia." (PMID 25071450, 2014). "The most common nDNA-PMD was dilated cardiomyopathy with ataxia syndrome (DCMA), also known as 3-methylglutaconic aciduria type V (OMIM#610198), due to biallelic pathogenic variants in DNAJC19 (MIM#608977)." (PMID 39533303, 2024). "Of note, mutations in DnaJC19, probably a member of the TIM complex, have been reported to cause dilated cardiomyopathy with ataxia, a Barth-like syndrome." (PMID 25111180, 2014). "The exact role of DNAJC19 is not fully characterized in humans, but pathological variants have been found to induce a phenotype of cardiomyopathy and ataxia, similar to Barth syndrome." (PMID 33426505, 2020). "Clearly, DNAJC19 and another mitochondrial J protein, DNAJC15, are not redundant as DnaJC15 does not rescue DnaJC19 mutations that lead to dilated cardiomyopathy and cerebellar ataxia." (PMID 25071450, 2014). "Mutations in DNAJC19 were related to DCMA syndrome, a novel autosomal recessive syndrome characterized by early-onset DCM, non-progressive cerebellar ataxia, testicular dysgenesis, growth failure, mild developmental delay, and 3-methylglutaconic aciduria." (PMID 34651031, 2021).
dilated cardiomyopathy (14 papers, 2014 to 2025). Cardiomyopathy which is characterized by dilation and contractile dysfunction of the left and right ventricles. "Interestingly, genes coding for mitochondrial proteins, such as TAZ, DNAJC19, or SDHA, were responsible for dilated cardiomyopathy." (PMID 40806260, 2025).
cardiomyopathy (6 papers, 2012 to 2023). A disease of the heart muscle or myocardium proper. "Genes important in these processes and that are associated with cardiomyopathy include DNAJC19, MAGMAS, TIMM50, MIPEP, XPNPEP3, HTRA2, CLPB and HSPD1." (PMID 35328774, 2022). "The human homolog of CG7394, DNAJC19, is associated with cardiomyopathy." (PMID 22715409, 2012). "The downregulation of DNAJC19 is closely with mitochondrial injury-related cardiomyopathy, autism, and other diseases." (PMID 36854759, 2023). "It is important to note that while mutations in DNAJC19 are associated with DCM, mutations in MAGMAS are not always associated with cardiomyopathy." (PMID 35328774, 2022).
Barth syndrome (3 papers, 2019 to 2021). Barth syndrome (BTHS) is an inborn error of phospholipid metabolism characterized by dilated cardiomyopathy (DCM), skeletal myopathy, neutropenia, growth delay and organic aciduria. "DCMA is a rare and understudied autosomal recessive disorder thought to be related to Barth syndrome but caused by mutations in DNAJC19, a protein of unknown function localized to the mitochondria." (PMID 31803760, 2019). "Indeed, the DNAJC19-prohibitin complex may regulate cardiolipin remodeling by Tafazzin, and would explain the similar cardiac phenotype observed in Barth syndrome and DNAJC19 associated disorders." (PMID 34356047, 2021). "In cultured cells, knock-down of DNAJC19 expression was reported to affect CL remodeling, which may explain the related clinical features of DCMA and Barth syndrome." (PMID 31803760, 2019).
autism (2 papers, 2012 to 2023). Persistent deficits in social interaction and communication and interaction as well as a markedly restricted repertoire of activity and interest as well as repetitive patterns of behavior. "The expression of DNAJC19, DNM1L, LRPPRC, SLC25A12, SLC25A14, SLC25A24 and TOMM20 were consistently reduced in at least two of the brain regions of autism patients compared to controls." (PMID 23116158, 2012). "The expression of DNAJC19, DNM1L, LRPPRC, SLC25A12, SLC25A14, SLC25A24 and TOMM20 were reduced in at least two of the brain regions of autism patients." (PMID 23116158, 2012). "Among these, DNAJC19 was downregulated in the MC and THL of autism patients." (PMID 23116158, 2012).
cryptorchidism (1 paper, 2020). The failure of one or both testes of a male fetus to descend from the abdomen into the scrotum during the late part of pregnancy. "For example, the ovarian failure in Perrault syndrome and the genital abnormalities (e.g., cryptorchidism/hypospadia) associated with variants in HSPA9 and DNAJC19 could be due to altered levels of sex hormones." (PMID 33171986, 2020).
lung carcinoma (1 paper, 2021). "However, the oncogenic role of DNAJC19 and the associated underlying mechanisms in lung cancer are still far from elucidated." (PMID 34217321, 2021). "Taken together, these results suggest that shRNA-mediated inhibition of DNAJC19 impairs cell growth, viability, migration and invasion in lung cancer cell lines." (PMID 34217321, 2021). "Next, we overexpressed AKT (Lv-AKT) in A549 lung cancer cells treated with DNAJC19 shRNA." (PMID 34217321, 2021). "First, we assessed the protein expression of DNAJC19 in different lung cancer cells." (PMID 34217321, 2021). "Therefore, we carried out in vitro experiments to investigate whether and how the DNAJC19 protein plays a role in lung cancer cells." (PMID 34217321, 2021).
microcytic anemia (1 paper, 2022). Anemia in which the red blood cell volume is decreased. "The index (IV‐2) did not have dysmorphic features, microcytic anemia, or hepatic dysfunction, although these phenotypes have been observed in several cases with 3MGA type V. The DNAJC19 gene is localized to the inner mitochondrial membrane." (PMID 35611801, 2022).
Nephropathy (1 paper, 2023). A nonspecific term referring to disease or damage of the kidneys. "However, the role of lncRNA DNAJC19 in nephropathy is not clear." (PMID 36854759, 2023).
Sengers syndrome (1 paper, 2025). Congenital cataract - hypertrophic cardiomyopathy - mitochrondrial myopathy (CCM) is a mitochondrial disease characterized by cataracts, hypertrophic cardiomyopathy, muscle weakness and lactic acidosis after exercise. "All affected individuals had a homozygous pathogenic variant in DNAJC19 encoding the TIMM14 component of the IMM protein import system, thus showing aetiological similarities to Sengers syndrome." (PMID 38872485, 2025).
stomach adenocarcinoma (1 paper, 2019). "The stomach adenocarcinoma dataset revealed that overall survival was significantly altered as a result of differential expression of four HSPs - CCT8, DNAJC19, GAK and SEC63." (PMID 30578123, 2019).
stomach cancer (1 paper, 2019). "The overexpression of DNAJC19, which encodes for the protein TIM14, has yet to be shown to influence oncogenesis or patient survival in stomach cancer." (PMID 30578123, 2019).
cancer (3 papers, 2020 to 2024). A tumor composed of atypical neoplastic, often pleomorphic cells that invade other tissues. "Of interest, 16 (16/22, 72.7%) of them are HSP40 family members, including DNAJC28, which was associated with 10 hallmarks across 8 cancers; DNAJC19, which was associated with 8 hallmarks across 5 cancers; and DNAJC30, which was associated with 6 hallmarks across 5 cancers." (PMID 33225964, 2020). "An upregulation of TRAP1, DNAJA3, and DNAJC19 genes is observed across different cancers, offering anti-apoptotic signals to maintain and sustain tumor dormancy." (PMID 38994941, 2024). "DNAJC19, also named translocase of the inner mitochondrial membrane 14 (TIMM14), is responsible for maintaining the integrity of mitochondria and is linked to cardiovascular disease, as well as cancers." (PMID 34217321, 2021). "In contrast, DNAJC19 was negatively enriched in 26 cancer types, including BRCA (FDR < 0.0001)." (PMID 33225964, 2020). "In addition, the DNAJC19 expression level was diverse in different cancer cases." (PMID 34217321, 2021). "Furthermore, a study that characterized HSP based on the thematic hallmarks of cancers found a surge in the TRAP1 (HSP75), DNAJA3 (TID1), and DNAJC19 (HSP40 C19 member) (HSP40 family proteins) genes across different cancers, proffering anti-apoptotic signals." (PMID 38994941, 2024). "As expected, compared to noncancerous adjacent tissue, cancer tissue showed significant overexpression of DNAJC19." (PMID 34217321, 2021).
tumor (3 papers, 2021 to 2024). "This raises the possibility that overexpression or mutation of DNAJC19 is associated with tumor development and progression." (PMID 34217321, 2021). "Mitochondrial dysfunction due to changes in DNAJC19 is a common phenotype of tumor cells and is supposed to contribute to the initiation, development and progression of many solid cancers." (PMID 34217321, 2021). "In brief, we found for the first time that shRNA-mediated repression of DNAJC19 greatly attenuated tumor cell growth and metastasis by regulating PI3K/AKT signaling, providing a novel therapeutic target for NSCLC patients." (PMID 34217321, 2021). "Our data show that DNAJC19 is overexpressed in NSCLC tumor tissues compared to normal tissues." (PMID 34217321, 2021). "Finally, we found for the first time that shRNA-mediated repression of DNAJC19 greatly attenuated tumor cell growth and intrapulmonary metastasis by regulating PI3K/AKT, highlighting DNAJC19 as a novel therapeutic target for treating NSCLC patients." (PMID 34217321, 2021). "Interestingly, we found that DNAJC19 increased tumor metastasis and affected xenograft tumor growth in a nude mouse model." (PMID 34217321, 2021). "Furthermore, the mouse xenograft model showed that tumor size and weight were significantly decreased in the DNAJC19-knockdown group compared with the negative control group." (PMID 34217321, 2021).
DNAJC19 also shares sentences with these, for which no sentence is quoted: 3-methylglutaconic aciduria type 5 (4 papers); cerebellar ataxia (2); developmental delay (2); and heart disorders (1); breast carcinoma (1); cardiovascular disease (1); Cerebellar atrophy (1); cerebral aneurysms (1); distal motor neuropathy (1); hypospadias (1); limb-girdle muscular dystrophy type 1D (1); lipodystrophy (1); non-small cell lung carcinoma (1); ovarian carcinoma (1); ovarian failure (1); Perrault syndrome (1); phenylketonuria (1); pituitary adenomas (1); schizophrenia (1).